GZMB (granzyme B)
Diseases named in the same sentence as GZMB in open-access papers (continued):
Sharing a sentence is not in itself a finding about the gene and the disease.
tumor (continued). "However, the CD8+ T cell infiltrate was largely negative for both Granzyme B and TIA-1, suggesting these T cells were not capable of effective tumor lysis." (PMID 33603731, 2021). "MAIT cells from responders also had higher levels MAIT cells in the melanoma lesions than non-responders, as well as increased levels of GZMB, indicating that MAIT cells from responders have higher cytotoxic functions while circulating and infiltrating the tumor site." (PMID 33805904, 2021). "There were no changes in total CD8+ T cells in the tumor, but there were significant increases in multifunctional CD8+ T cells (CD8+IFN-γ+GzmB+) and CD8+ T cells with a proliferative capacity (CD8+Ki67+) following PRGN-2009 treatment compared with empty vector control." (PMID 33651712, 2021). "Yet, this experimental system did not allow us to formally rule out a potential role for another EP4 and granzyme-B-expressing cell population or of an EP2-expressing cell subset, besides NK cells, that might contribute to tumor control in GPP mice." (PMID 33220234, 2020). "In the G-CSFR−/− mice compared to WT mice, the expression of granzyme B, perforin, and FasL at the mRNA level was increased over 2-fold suggesting an increase in cytotoxic activity in the absence of G-CSFR in all immune cells, but not tumor cells." (PMID 33042110, 2020). "Although the induction of anti-tumor T-cell responses, including upregulation of IFNγ and GzmB on CD8+ T-cells, in irradiated tumors has been detected, the proper trafficking of effector T-cells into the tumor microenvironment may not always occur." (PMID 33419318, 2020). "(d) Granzyme B and perforin production were compared in the supernatants (n = 5), which CD3+ T cells of patients with GC were co-cultured with autologous mast cells from non-tumor or tumor tissues with or without anti-PD-L1 antibody." (PMID 30808413, 2019). "These included non-persisting infection with attenuated N-tropic F-MLV (F-MLV-N) or transient env124–138 peptide immunization, which failed to induce GzmB+ cells, and transplantation of the FV-induced FBL-3 tumor cell line, which induced moderate levels of GzmB+ cells." (PMID 27806296, 2016). "By contrast, the expression of proteins contained in lytic granules, Granzyme B and Perforin, was not dependent on SOCE at least in response to TCR stimulation of Ova-specific CTLs following coincubation with EG7-Ova tumour cells." (PMID 23922331, 2013). "This non-classical production of GZMB contributes to various biological processes including inflammatory responses, regulation of angiogenesis, and ECM degradation, thereby exerting immunosuppressive effects and underscoring its multifaceted role in tumor initiation and progression." (PMID 41567188, 2025). "However, Granzyme B + CD8 + T cells were reduced by PAK1KO, contributing to no change in granzyme B + CD8 + T cells and less increase in granzyme B and perforin double positive cytotoxic CD8 + T cells in double KO tumour." (PMID 38797819, 2024). "Moreover, we conducted in vitro experiments to prove that, exogenous overexpression of GBP5 in T cells fails to augment their tumor-killing efficacy, while elevated GBP5 expression in OC cells does not directly enhance the secretion of GZMB and IFNγ from T cells." (PMID 38817865, 2024). "The levels of GzmB, a key mediator of the cytotoxic activity of CD8+ T cells, in the culture supernatants of CD8+ T cells of the immunized mice were 14 times greater in their cultures with MC38 tumor cells than in their cultures without the tumor cells (p < 0.001)." (PMID 38247803, 2024). "While in vitro tumour lysis of PD-L1+ tumour cells was not improved by the addition of an IFP to the CAR T cells, their cytokine secretion in terms of IFN-γ, IL-2 and Granzyme B concentration in the coculture supernatant was higher than control T cells that were transduced with CAR only." (PMID 37400680, 2023).
tumor (continued). "The lung adenocarcinoma, a partial metabolic responder, had a granzyme B PET tumor SUVmax of 4.1 and a tumor-to-blood ratio of 1.2, whereas the sarcomatoid carcinoma was determined to be a partial nonresponder, with a tumor SUVmax of 2.0 and a tumor-to-blood ratio of 0.8." (PMID 36460341, 2023). "Surprisingly, we did not observe a difference in GzmB or Prf1 expression between CD8+ T-cells isolated from MC38 tumors between groups, suggesting that impaired T-cell mediated anti-tumor immune responses are unlikely to explain the increased tumor burden observed in LysMCre/+;Mycfl/fl hosts." (PMID 36552868, 2022). "Interestingly, the CD8prolif cluster was connected to the CD8GZMB clusters but not the other cytotoxic clusters, suggesting that GZMB expressing cells are the primary CD8+ T cell population undergoing proliferation and clonal expansion in the tumor microenvironment." (PMID 35831288, 2022). "It has been reported that CD8+ T cell infiltration in differentiated thyroid cancer is correlated with increased tumor recurrence, but there are reports of the contrary, that CD8+ T cell infiltration is correlated with improved DFS, because CD8+ T cell is in anergy without granzyme B." (PMID 36293435, 2022). "Also, to exclude the impacts of EL4 exosomes on the cytotoxicity of OT-I CTLs and the vitality of tumor cells, we tested the proliferation and cytotoxic cytokine production of OT-I cells, including IFN-γ, granzyme B, perforin, and TNF-α, and no significance changes were found." (PMID 34172932, 2021). "Moreover, tumor pathology examination after 10 days revealed increased expression of the transcription factors T-bet and Eomes and effector molecules IFN-γ and granzyme B in miR-23a-inhibited CTLs, despite CTL persistence within the tumor mass was not affected." (PMID 34830805, 2021). "However, after PD-1 blockade with Nivolumab, these cells regained their proliferative and cytotoxic potential in vitro, measured by higher expression of granzyme B and perforin, while CD8+ T cells from tumor samples with low infiltration of IL-9+ cells did not respond to anti–PD-1 treatment." (PMID 33777008, 2021). "Low concentration of IL-24 did not affect either perforin or granzyme B expression in CD8+ T cells (Tukey tests, P > 0.05), while high concentration of IL-24 promoted perforin and granzyme B expression in both peripheral and tumor-infiltrating CD8+ T cells (Tukey tests, P < 0.05)." (PMID 31921658, 2019). "Therefore, it might not be surprising that genes such as GZMB and CXCL10, which are expressed by non-cancerous cells, were among top ones predicted to be induced by intra-tumor microbiota." (PMID 30294508, 2018). "However, the anti-tumour activity as indicated by AB1 lysis and IFN-γ/granzyme B production by CD8+ T cells was no longer influenced when co-cultured with Splenocytes of mice receiving celecoxib diet, indicating that COX-2 inhibition leads to a reduction in suppressive immune cells." (PMID 20804550, 2010). "Furthermore, the activation level of tumor-infiltrating CD8+ T cells was unchanged in the absence of Rela, leaving the proportion of cytokine-producing cells following PMA-ionomycin restimulation unaltered, with the exception of a slight increase in GzmB+ CD8+ T cells in Rela-cKOCD8 mice." (PMID 38504985, 2024). "Notably, and contrary to previous reports, we found that the expression of both granzyme B and Ki67 was almost exclusively limited to TOX+CD8+ T cells, demonstrating that these cells, despite showing high expression of PD-1 and TOX, are not functionally exhausted in this tumour model." (PMID 35508656, 2022). "Moreover, granzyme B (GZMB) transcription was elevated in tumor lesions given CDA and celecoxib co-treatments but was not elevated after CDA monotherapy, suggesting that activated effector T cells expressing GZMB accumulated in tumor lesions only if celecoxib was combined with late CDA treatment." (PMID 32847988, 2020).
tumor (continued). "Considering T-bet does not appear regulate GzmB expression and the high levels of Prdm1 mRNA observed in CD4+ Th-ctx cells post-αCTLA-4 treatment, we explored whether Blimp-1 contributed to the acquisition of a cytotoxic phenotype by CD4eff T cells and to the overall anti-tumor activity of αCTLA-4." (PMID 31924474, 2020). "We next investigated whether tumor cell-induced NK cell granule polarization was affected by CD38 by analyzing the translocation of cytolytic granules containing perforin and granzyme B. In the absence of target cells, perforin and granzyme B displayed dispersed granules in NK cells." (PMID 25879940, 2015). "Thus, we next determined by IHC whether Granzyme B was being affected by RFA treatment alone or in combination with AB680 in the long term (Post 10D) and compared the results with a standard KPC subcutaneous tumor grown up to 10 days (Control) which received no treatment." (PMID 36147911, 2022).
cancer (519 papers, 1997 to 2026). A tumor composed of atypical neoplastic, often pleomorphic cells that invade other tissues. "The KEGG enrichment network analysis of differentially expressed genes (DEGs) revealed their predominant enrichment in the Pathways in cancer, these findings strengthen the association between GZMB/PRF and the regulation of apoptosis and cell cycle." (PMID 41244830, 2025). "Cytotoxic CD4+ T cells have been identified in cancers and associated with GZMB and Perforin (PRF) expression via the transcription factor EOMES." (PMID 40492347, 2025). "Nevertheless, it is supported that in spite of the favorable outcome associated with GZMB expression in tumors, its expression in some cases was associated with poor prognosis, resistance to therapy, and advanced cancer stage." (PMID 38067341, 2023). "Differential levels of granzyme B (GzmB) have been associated with multiple disorders, from cancer to infection or auto-immune diseases." (PMID 37376918, 2023). "One study found that 20 out of 22 gasdermin E mutations identified within cancer samples were associated with reduced pyroptosis in response to granzyme B." (PMID 35401556, 2022). "Clinically, during the early phase of PDAC development, TGF-β1 expression is inversely associated with granzyme B (GzmB), a cytolytic granule that plays a pivotal role in natural killer (NK) cell-mediated cytotoxicity against early-stage cancers." (PMID 34862460, 2022). "As a result, loss of Bid expression in cancer cells leads to reduced sensitivity to granzyme B-induced apoptosis." (PMID 35401556, 2022). "Overall, these results indicate that the resistance to lymphocyte cytotoxicity following cancer-cell irradiation can result from both a loss in direct lysis by perforin and reduced uptake of granzyme B." (PMID 35042775, 2022). "Our results revealed that high LMS was positively associated with the expression of CTLA4, PDCD1, TIGIT and GZMB in the EC and pan-cancer cohorts." (PMID 35834061, 2022). "On the other hand, with the higher production of granzyme B of NK cells in the IL-15 mDCs (6 days group), associated with enhance cytotoxicity with CD107a degranulation assay against K562 cancer cells compared to other groups." (PMID 35413499, 2022). "The association between granzyme B and immunosuppressive effects in Tregs was initially established based on the frequent presence of GrB+ Tregs in malignant tumor lesions." (PMID 33868318, 2021). "We found that cancer cell–derived WFDC2 negatively correlated with granzyme B+ CD8+ cytotoxic T cell (CD8_4) density and was associated with poor HGSC patient survival." (PMID 33917869, 2021). "Granzyme B expression in post-therapy tumors has been associated with the immune therapy response in cancer." (PMID 34832863, 2021). "Of the various human apoptosis-inducing enzymes, granzyme B (GrB)-mediated apoptosis of target cells has been clinically associated with improved patient outcomes for various types of cancers." (PMID 29925790, 2018). "The in vitro cytotoxicity assay indicated that GzmB-encapsulated nanogels had targeted toxicity against CD44-overexpressing HCT-116 cancer cells, while CD44-deficient cells showed little cytotoxic effect." (PMID 28181831, 2017). "With Bcl-2, we studied an anti-apoptotic cytosolic protein that can decrease the susceptibility of cancer cells to induction of apoptosis by granzyme B." (PMID 26510188, 2015). "In response to infection or cancer, the cytotoxic granule granzyme B associates with perforin in NK cells to form a complex which is ultimately released into the cytoplasm of the target cell and mediates the cytotoxic effects of NK cells." (PMID 24138752, 2013). "Furthermore, HNSCC cancer cells that overexpress heat shock protein 70 (Hsp70) become more susceptible to lysis by NK, confirming the important role of granzyme B in cancer apoptosis." (PMID 40766321, 2025).
cancer (continued). "Furthermore, studies have shown that low levels of GZMB expression were associated with a better probability of survival in certain cancers." (PMID 40002821, 2025). "Conversely, granzyme B has complex perforin-independent and receptor-mediated functionalities and its expression in B cells and plasmacytoid DC has been associated with T cell regulation in inflammatory diseases and cancer." (PMID 41497979, 2025). "To test whether the enhanced cytotoxicity of PD-1high CAR-T cells is associated with the differential expression of anti-cancer effector molecules after T cell activation, we measured intracellular perforin and granzyme B levels." (PMID 37388744, 2023). "Furthermore, cisplatin can make cancer cells more susceptible to granzyme B by increasing the penetration of cancer cells and the expression of the granzyme-target caspase-3, which mediates the implementation phase of apoptosis." (PMID 38057843, 2023). "However, as in parallel the rate of granzyme B positive cells tended to be lower in the case of more epitopes being affected by mutation (p = 0.099), the anti-cancer effect of the increased CD8-positive cell infiltration seems to be ineffective." (PMID 35327977, 2022). "Indeed, HLA class I antigen down-regulation is associated with a decreased recognition of cancer cells by cognate CD8+/Granzyme B+ T cells." (PMID 30458852, 2018). "In the present study, our aim was to investigate whether a frequent genetic variation of GZMB, the gene encoding GrB, constituted by three missense single nucleotide polymorphisms (rs2236338, rs11539752 and rs8192917) has any association with cancer risk in individuals with LS." (PMID 36890824, 2023). "Combined with the fact that IL-2 concentration would experience a phased increase during immune responses, the results above could partially explain T cell exhaustion within TME in the case of malignancies and underline the significance of granzyme B in the setting of immunosuppression." (PMID 33868318, 2021). "Studies on granzyme B in cancer cell apoptosis have shown that these cells can be resistant to apoptosis induced by this enzyme." (PMID 40766321, 2025). "Strategies that harness or enhance the activity of Granzyme B are being developed for treating cancers and infectious diseases, although delivery and stability remain areas of active research." (PMID 40766321, 2025). "In AML, however, the levels of GZMB are notably diminished, undermining its role as a crucial cytotoxic mediator for T and NK cells in combatting cancer cells." (PMID 40608798, 2025). "Following the SNV analysis, we examined the proportion of heterozygous and homozygous mutations (both deletions and amplifications) in GZMA, GZMB, GZMK and PRF1 in the different cancers." (PMID 40002821, 2025). "GZMB is a serine protease released by cytotoxic T lymphocytes and NK cells, playing a key role in the elimination of cancer cells through the induction of apoptosis." (PMID 40766321, 2025). "The analysis of copy number variation (CNV) mutations in GZMA, GZMB, GZMK and PRF1 across the various cancer types revealed significant associations with survival outcomes, highlighting their potential prognostic value." (PMID 40002821, 2025). "Granzyme B (GZMB) is crucial in cytotoxic T lymphocytes and NK cells for killing infected and cancer cells." (PMID 40236693, 2025). "To further explore the impact of the SNV and CNV mutations in GZMA, GZMB, GZMK and PRF1 in the different cancers, we assessed the survival differences between mutant and wild-type forms of the genes." (PMID 40002821, 2025). "The serine protease granzyme B is a key component of cytotoxic granules released by T cells that facilitates T cell-mediated cancer cell killing." (PMID 40346068, 2025). "The accumulated results highlight the multifaceted role of GZMB in different types of cancer and its potential as a therapeutic target." (PMID 40766321, 2025).